RNU6-1219P (RNA, U6 small nuclear 1219, pseudogene)
Gene: Small nuclear RNA gene on chromosome 22 (29,191,697 to 29,191,808, reverse strand). Ensembl gene ENSG00000251952.
Homologues: Orthologues: chimpanzee U6 (73% identical), guinea pig U6 (52% identical). Paralogues in human: RNU6-560P (72% identical), RNU6-774P (72% identical), RNU6-1209P (71% identical), RNU6-1214P (71% identical), RNU6-411P (71% identical), RNU6-1340P (71% identical), RNU6-144P (71% identical), RNU6-340P (71% identical), RNU6-444P (71% identical), RNU6-590P (71% identical), RNU6-59P (71% identical), RNU6-742P (71% identical), and 1284 more.